IDH1 (isocitrate dehydrogenase (NADP(+)) 1)
Diseases named in the same sentence as IDH1 in open-access papers (continued):
Sharing a sentence is not in itself a finding about the gene and the disease.
glioblastoma (continued). "We collected information of survival time, MGMT methylated status, CIMP status, and IDH1 mutant status from TCGA glioblastoma cohort." (PMID 31450822, 2019). "Based on the genetic status of IDH1, glioblastomas are now divided into IDH1-wildtype glioblastoma and IDH-mutant glioblastoma, whereas the latter one largely overlaps with secondary glioblastoma in older classifications." (PMID 31242696, 2019). "Given the known prognostic impact of IDH1 mutation on survival, we investigated the association of PIK3CA mutation with PFS and OS after excluding 12 IDH1 mutant glioblastomas." (PMID 31036078, 2019). "According to some data, the frequency of IDH1 and IDH2mutations in intracranial astrocytomas and glioblastomas is 68% and12%, respectively." (PMID 31413876, 2019). "Both IDH1 and IDH2 mutation were favorable prognostic factors of lower-grade gliomas distinguished from primary glioblastomas." (PMID 31708732, 2019). "The most prevalent mutation in IDH1, R132H (IDH1R132H), was originally identified in acute myeloid leukemia (AML) and glioblastoma multiforme (GBM)." (PMID 31151327, 2019). "A study by Adilijiang and colleagues assessed the impact of BEV alone and in conjunction with temozolomide in the treatment of both newly diagnosed IDH1 wildtype and mutant glioblastoma." (PMID 31689995, 2019). "Essentially LGG has mild nuclear atypia, moderate pleomorphism, high degree of cellular differentiation, and low MIB-1, with intrinsic capacity to progress to IDH1 mutant anaplastic astrocytoma or glioblastoma." (PMID 31853670, 2019). "Within the remaining 145 IDH1 wildtype glioblastoma patients, the difference in PFS between PIK3CA mutant and PIK3CA wildtype tumors was statistically significant by Wilcoxon test (p = 0.02) and was a trend to significance by log-rank test (p = 0.11)." (PMID 31036078, 2019). "In accordance with these findings, IDH1 silencing of U87, A172, and U138 glioblastoma cell lines reduced levels of NADPH, deoxynucleotides and glutathione and increased their sensitivity to radiation-induced senescence." (PMID 31242696, 2019). "A possible reason is that our model was generated by genetically engineering glioblastoma cells to express mutant or wild type IDH1." (PMID 30833594, 2019). "Survival benefit from surgical resection varies according to IDH1 genotype in glioblastomas, as better prognosis is observed in the IDH1 mutant subgroup following maximal surgical resection." (PMID 30374421, 2018). "WHO considers all the IDH1-wildtype patients, which are roughly 95% of the glioblastoma patient population, to have relatively poor prognosis." (PMID 29572492, 2018). "Mutations in cytosolic IDH1 isoform occur in approximately 80% of all lower-grade glioma (LGG) and secondary glioblastoma." (PMID 29303363, 2018). "BCAT1 expression in glioblastoma tumors is specific to those carrying wild-type isocitrate dehydrogenase 1 and 2 (IDH1 and IDH2)." (PMID 29211698, 2018). "For instance, overexpression or amplification of EGFR, mutations in IDH1 and IDH2 and phosphatase and tensin homologue (PTEN) mutations contribute to the pathogenesis of glioblastoma." (PMID 30382873, 2018). "A study has shown that the siRNA knockdown of either IDH1 or IDH2 can significantly reduce the proliferative capacity of a glioblastoma cell line expressing both wild-type IDH1 and IDH2." (PMID 29661250, 2018). "IDH1 WT glioblastomas display an aggressive behavior with tumor infiltration along white matter structures and the formation of neovessels." (PMID 30686972, 2018). "Mutations in either IDH1 or IDH2, commonly seen in glioblastomas, contribute to downregulation of BCAT1 through DNA methylation of the BCAT1 promoter and the corresponding epigenetic silencing of BCAT1." (PMID 29211698, 2018).
glioblastoma (continued). "The particularity of this study is the extreme homogeneity of the patient casistics, which is made by all IDH1 wildtype primary glioblastoma." (PMID 29844869, 2018). "Secondly, IDH1/2 wild-type subgroup showed similar PD-L1 expression as found in glioblastoma multiforme." (PMID 28178682, 2017). "We compared triple-positive samples with oligodendroglioma, IDH1 mutation only subgroup with astrocytoma and TERT mutation only tumors with glioblastoma since these genetic events highly represent histological diagnosis." (PMID 28915860, 2017). "In concordance with our findings in the virally transduced glioblastoma cell lines, HCT116 IDH1-R132H cells (heterozygous knock-in mutation) showed higher sensitivity to ABT263 with a threefold decrease of the IC50 value." (PMID 29057925, 2017). "Exons 4 of IDH1 and IDH2 genes were screened in all cases of glioblastoma targeting possible mutations." (PMID 28785587, 2017). "Several studies showed that the IDH1 mutation is inversely associated with grade in diffuse glial tumors, affecting 71% of grade II, 64% of grade III, and 6% of primary glioblastomas." (PMID 28392842, 2017). "These gene expression data were correlated with IDH1 mutational status in 677 LGG and glioblastoma samples derived from The Cancer Genome Atlas (TCGA)." (PMID 28467784, 2017). "In contrast to previous reports that IDH1 R132H mutations promote survival, we confirmed that miR-148a increased cell migration and invasion by downregulating GADD45A in IDH1R132H glioblastomas." (PMID 28445981, 2017). "The tumors of cluster 1 were highly malignant and belonged to high WHO grade, classical and mesenchymal subtypes, G3 subgroup, glioblastoma and harbored wild type isocitrate dehydrogenase 1 (IDH1)." (PMID 28977840, 2017). "The functional utility of the antibody to specifically detect mutant IDH1 protein in astrocytomas, oligodendrogliomas, and glioblastomas is also examined through immunohistochemical analysis." (PMID 31548536, 2017). "Overall, the standard histopathology review was consistent with a typical glioblastoma patient population with a low number of IDH1 R132H+ tumor specimens." (PMID 28481241, 2017). "BRAF mutation and IDH1 mutation identify glioblastomas with less aggressive clinical course and H3F3A-K27M mutation defines glioblastomas with dismal prognosis." (PMID 26452024, 2016). "Therefore, IDH1 mutation could be used to differentiate primary from secondary glioblastoma." (PMID 26858939, 2016). "In this study, we sought to stratify young adult glioblastomas by BRAF, H3F3A and IDH1 mutations and examine the clinical relevance of the biomarkers." (PMID 26452024, 2016). "Mutations in IDH1 and IDH2 were found in 75 % of grade 2–3 gliomas and secondary glioblastoma, and in about 20 % of AML." (PMID 26812134, 2016). "In summary, our study demonstrates recurrent BRAF, IDH1 and H3F3A mutations in young adult glioblastomas with clinical impacts." (PMID 26452024, 2016). "Similar pattern of IDH1 expression was shown in neurospheres derived from glioblastoma primary cultures." (PMID 27145078, 2016). "In summary, our study demonstrates the clinical values of stratifying young adult glioblastomas with BRAF, H3F3A and IDH1 mutations, which has important implications in refining prognostic classification of glioblastomas." (PMID 26452024, 2016). "Our findings are also in agreement with a previous study showing that SLC16A3 (MCT4) mRNA levels were lower in patient-derived mutant IDH1 models compared to wild-type IDH1 glioblastoma models." (PMID 27144334, 2016).
glioblastoma (continued). "Tumor-relevant levels of 2-HG were added for 48 h to U-251 MG (IDH1 wild type) glioblastoma cells and potential changes in DUSP16, PTPRG and PTPRT expression levels were monitored." (PMID 27586084, 2016). "Initially, a pivotal study profiling IDH1 wild-type and mutant glioblastoma cells with liquid chromatography–mass spectrometry has reported high levels of the metabolite 2-HG in mutant cells." (PMID 26858939, 2016). "The determination of IDH1 status in glioblastoma will likely be an early step in treatment algorithms for patients suffering from this tumor." (PMID 26858939, 2016). "Comparing PDGFRA expression across BRAF, IDH1 and H3F3A mutated glioblastomas, positive expression co-occurred in 50% (10/10) of H3F3A mutated tumors, 27.8% (5/13) of IDH1 mutated tumors and 12.5% (2/16) of BRAF mutated tumors (p = 0.05)." (PMID 26452024, 2016). "It seems that AQP4-M23/M1 ratio is higher in the more malignant IDH1-negative glioblastomas than in the IDH1-positive astrocytomas." (PMID 27483250, 2016). "This type of analysis successfully elucidated the preferred locations of IDH1/2 mutated and MGMT promoter methylated glioblastoma." (PMID 27716832, 2016). "Previously, we demonstrated that the IDH1 c.G395A; p.R132H mutation was associated with longer survival in grade II astrocytoma and GBM (Glioblastoma)." (PMID 27834917, 2016). "In 107 glioblastomas aged from 17 to 35 years, mutually exclusive BRAF-V600E (15%), H3F3A-K27M (15.9%), H3F3A-G34R/V (2.8%) and IDH1-R132H (16.8%) mutations were identified in over half of the cases." (PMID 26452024, 2016). "Geriatric glioblastoma (GBM) patients have a poorer prognosis than younger patients, but IDH1/2 mutations (more common in younger patients) confer a favorable prognosis." (PMID 27579614, 2016). "Apart from the markers of stemness, all of the cells presented expression of wild type IDH1 at levels comparable to normal neural cells and neurospheres derived from glioblastoma primary culture." (PMID 27145078, 2016). "Future perspectives in neuro-oncology will bring the concurrent assessment of IDH1/2 mutations and MGMT promoter methylation status for glioblastoma and 1p/19q co-deletion for oligodendroglioma." (PMID 27379174, 2016). "IDH1 mutation, MGMT promoter methylation, and gene expression profiling can segregate newly diagnosed glioblastoma patients into groups with different prognoses." (PMID 26646075, 2015). "Of the 274 patients enrolled in this study, the status of IDH1/2 mutation and MGMT promoter methylation was analyzed in 229 glioblastomas." (PMID 26503470, 2015). "The secondary glioblastoma and the low-grade diffuse astrocytoma represent the largest groups of IDH1 positivity, followed by oligoastrocytoma/oligo-dendroglioma in 50.0% of cases, and anaplastic astrocytoma in 47.36%." (PMID 27275230, 2015). "For example, isocitrate dehydrogenase 1 (IDH1) gene was found mutated in over 70% of WHO grade II and III astrocytomas and oligodendrogliomas and in glioblastomas that developed from lower grade lesions." (PMID 25923219, 2015). "To achieve this objective, we analyzed two genetically engineered IDH1 mutant cell models, a U87 glioblastoma cell line-based model and an E6/E7/hTERT immortalized Normal Human Astrocyte (NHA)-based model." (PMID 25706986, 2015). "In contrast other similar study showed reactivity of IDH1 in a minority of glioblastoma with PNET component and argue against the sole of secondary glioblastoma." (PMID 27275230, 2015). "This possibly reflects the CpG island hypermethylator subclass of glioblastomas, which is positively correlated with survival and for which IDH1 is an important regulator." (PMID 25953855, 2015).
glioblastoma (continued). "In other cancer types hypermethylated subgroups were associated with IDH1 mutations (AML, glioblastoma), or EBV virus (gastric cancer)." (PMID 26545983, 2015). "IDH1 mutations occur at high frequency in WHO grade II and III astrocytoma (>80% of cases), precursor lesions of secondary glioblastoma, whereas IDH2 mutations occur largely in oligodendroglial tumors, with much lower frequency." (PMID 25785247, 2015). "Lastly 1 out of 2 glioblastomas with oligodendroglioma component showed IDH1 cytoplasmic positivity." (PMID 27275230, 2015). "It has recently been shown that glioblastomas with the CpG island methylator phenotype (CIMP) are associated with the proneural subgroup of tumours and are driven by IDH1 mutation." (PMID 24868540, 2014). "Consistently reported prognostic factors for glioblastoma (GBM) are age, extent of surgery, performance status, IDH1 mutational status, and MGMT promoter methylation status." (PMID 25233099, 2014). "Induction of G-CIMP+ state by exogenous expression of a mutated isocitrate dehydrogenase 1, IDH1-R132H, suppressed EGFR and H-Ras protein expression as well as pERK accumulation in independent glioblastoma models." (PMID 25277177, 2014). "Our smMIP technique detected amplification of PDGFRA, KIT and EGFR within tumor BI05, an IDH1-wild type glioblastoma." (PMID 25608559, 2014). "Further studies have demonstrated that IDH1 mutations are present in 50–90% of cases of grade II and III astrocytoma and oligodendroglioma, but rarely present in primary glioblastoma or pilocytic astrocytoma." (PMID 24932255, 2014). "It was also clear that there is a correlation between IDH1/2 mutation and MGMT methylation and also IDH1/2 mutation and PTEN status which is present in both grade III tumours and primary glioblastomas." (PMID 24952577, 2014). "It has been demonstrated that mutations of the IDH1 and IDH2 gene (IDH1R132, IDH2R172) in glioblastomas are associated with the production of the TET inhibiting oncometabolite 2-hydroxyglutarate." (PMID 24386123, 2013). "It has been reported that as high as 90% of diffuse and anaplastic gliomas and secondary glioblastomas (arising from a pre-existing low-grade astrocytoma) are IDH1-positive." (PMID 24252196, 2013). "Point mutations in genes encoding NADP+-dependent isocitrate dehydrogenases (especially IDH1) are common in lower grade diffuse gliomas and secondary glioblastomas and occur early during tumor development." (PMID 24252742, 2013). "The IDH1 or IDH2 genes are mutated in 50%–80% of astrocytomas, oligodendrogliomas or oligoastrocytomas of grades II and III, and secondary glioblastomas." (PMID 24202337, 2013). "We also found significantly elevated levels of D-2HG in IDH1-wt glioblastoma xenografts as compared to normal brain, although the levels were lower than in IDH1-mutant tumors (approximately 10-fold difference: 3.1 vs 0.33 nmol/mg)." (PMID 24252742, 2013). "Measurement of mitochondrial densities revealed a 2-fold increase in the number of mitochondria in the IDH1-mutant E478 tumor cells as compared to those in E434 anaplastic oligodendroglioma and the E98 glioblastoma xenograft lines." (PMID 24252742, 2013).
glioblastoma (continued). "Mutations that affect amino acid residue 132 of IDH1 were found in ∼70% of WHO grade II and grade III astrocytomas and oligodendrogliomas and in the secondary glioblastomas developed from these tumours." (PMID 23998913, 2013). "Mutations in isocitrate dehydrogenase (IDH)-1 or-2 are found in the majority of WHO grade II and III astrocytomas and oligodendrogliomas, and secondary glioblastomas." (PMID 23267435, 2012). "Further studies identified mutations in IDH1 affecting amino acid 132 in over 70% of WHO grade II and III astrocytomas, oligodendrogliomas, and secondary glioblastomas." (PMID 22885298, 2012). "Among the individual signature genes, both HOXD10 and TUSC3 remained correlated with age in both data sets when limiting the analysis to IDH1 wild-type glioblastoma cases." (PMID 23046790, 2012). "ATRX is frequently mutated in grade II-III astrocytomas (71%), oligoastrocytomas (68%), and secondary glioblastomas (57%), and ATRX mutations are associated with IDH1 mutations and with an alternative lengthening of telomeres phenotype." (PMID 22869205, 2012). "Recent mutational analyses also revealed that somatic mutations in the NADP-dependent isocitrate dehydrogenase genes, IDH1 and IDH2, were associated with an increased overall survival of glioblastoma patients." (PMID 21752281, 2011). "IDH1 has been implicated as a prognosis positive biomarker in glioblastoma and AML IDH1/2 mutants show hypermethylation in comparison to other AML subtypes." (PMID 22174824, 2011). "Relationships between molecular alterations also emerged: notably, EGFR alterations were positively correlated with both CDKN2A/B and PDGFRA alterations in IDH1/2-mutant astrocytoma, reflecting the cooccurrence of canonical glioblastoma molecular alterations in these tumors." (PMID 39164213, 2025). "The final pathological diagnosis was glioblastoma IDH1 R123H wild-type, WHO grade 4." (PMID 40291335, 2025). "Grade 4 IDH1/2-mutant astrocytomas and glioblastomas were more genomically distant from each other (median JD: 0.147) compared to genomic differences within grade 4 IDH1/2-mutant astrocytomas (median JD: 0.088) or within glioblastomas (median JD: 0.088, P < .001)." (PMID 39164213, 2025). "IDH1 or IDH2 mutations have been identified in more than 70% of CNS neoplasms diagnosed as grade II and III astrocytoma, oligodendroglioma, oligoastrocytoma, and secondary glioblastoma." (PMID 40546613, 2025). "Under the 2021 WHO classification, a diagnosis of glioblastoma (CNS WHO grade 4) requires the tumor to be a diffuse astrocytic glioma that is IDH (isocitrate dehydrogenase) gene (without a mutation in the IDH1 or IDH2 genes)." (PMID 41322297, 2025). "Previously, multivariate analyses revealed that patients with IDH1-mutant glioblastoma, now classified as grade 4 astrocytoma, and MGMT promoter methylation exhibited improved survival compared with patients having one or neither of these molecular alterations." (PMID 41149461, 2025). "The main prognostic factors for glioblastoma (GBM) are age, performance status, histologic grade, and the presence of specific molecular markers, such as MGMT methylation, IDH1/2 mutations, 1p19q codeletion, and EGFR overexpression, according to a new classification." (PMID 40723205, 2025). "Similar phenomena have been observed for genes like DDB2 in breast cancer and IDH1 in glioblastoma." (PMID 40427755, 2025).